TMEM19 (transmembrane protein 19)
Synonyms: FLJ10936
Tractability: Antibody: UniProt predicts a signal peptide or a membrane-spanning region. PROTAC: ubiquitination databases record sites on it; its protein half-life has been measured.
Gene: Protein-coding gene on chromosome 12 (71,686,082 to 71,705,047, forward strand). Ensembl gene ENSG00000139291.
Subcellular location: Membrane
Gene Ontology:
Molecular function: protein binding
Cellular component: membrane
Genetic constraint (gnomAD): Loss-of-function variants: 20 observed, 31.29 expected, observed/expected ratio (o/e) 0.64, 90% interval 0.45 to 0.93. The upper end of that interval is the gene's LOEUF score, 0.93, which puts it in group 3 of 6, group 1 being the genes least tolerant of losing a copy. Missense variants: 395 observed, 410.97 expected, observed/expected ratio (o/e) 0.96, 90% interval 0.88 to 1.04. Synonymous variants: 149 observed, 150.93 expected, observed/expected ratio (o/e) 0.99, 90% interval 0.86 to 1.13.
Homologues: Orthologues: chimpanzee TMEM19 (99% identical), macaque TMEM19 (98% identical), rabbit TMEM19 (93% identical), pig TMEM19 (91% identical), guinea pig TMEM19 (90% identical), rat Tmem19 (88% identical), mouse Tmem19 (87% identical), dog TMEM19 (82% identical), tropical clawed frog tmem19 (78% identical), zebrafish TMEM19 (52% identical), Drosophila melanogaster CG10171 (45% identical).
Diseases named in the same sentence as TMEM19 in open-access papers:
TMEM19 is named in the same sentence as 2 diseases in open-access papers, as found by Europe PMC text mining. Sharing a sentence is not in itself a finding about the gene and the disease.
TMEM19 shares sentences with these, for which no sentence is quoted: mammary tumors (1 paper); tumor (1).